Y_RNA (Y RNA )
Gene: Miscellaneous RNA gene on chromosome 7 (10,901,978 to 10,902,074, forward strand). Ensembl gene ENSG00000201774.
Homologues: Orthologues: chimpanzee Y_RNA (98% identical). Paralogues in human: RNY3 (93% identical), Y_RNA (93% identical), Y_RNA (92% identical), Y_RNA (91% identical), RNY3P1 (90% identical), Y_RNA (90% identical), Y_RNA (89% identical), RNY3P14 (88% identical), Y_RNA (88% identical), RNY3P16 (87% identical), Y_RNA (87% identical), RNY3P11 (86% identical), and 95 more.